TAS2R30 (taste 2 receptor member 30)
Description:
Receptor that may play a role in the perception of bitterness and is gustducin-linked. May play a role in sensing the chemical composition of the gastrointestinal content. The activity of this receptor may stimulate alpha gustducin, mediate PLC-beta-2 activation and lead to the gating of TRPM5 (By similarity).
Synonyms: T2R30; T2R47; TAS2R47
Tractability: Antibody: its Gene Ontology location is reachable by antibodies, with high confidence; UniProt predicts a signal peptide or a membrane-spanning region. PROTAC: a small molecule that binds it is known.
Target class: Membrane receptor; Taste receptor (taste family GPCR); Taste family G protein-coupled receptor
Gene: Protein-coding gene on chromosome 12 (11,132,958 to 11,134,644, reverse strand). Ensembl gene ENSG00000256188.
Subcellular location: Membrane
Pathways (Reactome):
Signal Transduction: Class C/3 (Metabotropic glutamate/pheromone receptors); G alpha (i) signalling events
Sensory Perception: Sensory perception of sweet, bitter, and umami (glutamate) taste
Gene Ontology:
Molecular function: bitter taste receptor activity; G protein-coupled receptor activity
Biological process: detection of chemical stimulus involved in sensory perception of bitter taste; G protein-coupled receptor signaling pathway; sensory perception of taste
Cellular component: membrane; plasma membrane
Genetic constraint (gnomAD): Loss-of-function variants: 0 observed, 0.0996 expected, observed/expected ratio (o/e) 0, 90% interval 0 to 1.89. That is too few expected variants to judge how well the gene tolerates losing a copy. Missense variants: 395 observed, 363.53 expected, observed/expected ratio (o/e) 1.09, 90% interval 1 to 1.18. Synonymous variants: 141 observed, 129.19 expected, observed/expected ratio (o/e) 1.09, 90% interval 0.95 to 1.25.
Homologues: Orthologues: chimpanzee TAS2R30 (97% identical), macaque TAS2R46 (79% identical), dog CAFA-T2R43 (58% identical), mouse Tas2r120 (46% identical), rat Tas2r120 (44% identical), rat Tas2r136 (43% identical), mouse Tas2r136 (42% identical). Paralogues in human: TAS2R46 (82% identical), TAS2R43 (78% identical), TAS2R31 (78% identical), TAS2R20 (66% identical), TAS2R50 (64% identical), TAS2R19 (64% identical), TAS2R14 (44% identical), TAS2R13 (42% identical), TAS2R7 (35% identical), TAS2R9 (35% identical), TAS2R10 (34% identical), TAS2R3 (32% identical), and 11 more.
Diseases named in the same sentence as TAS2R30 in open-access papers:
TAS2R30 is named in the same sentence as 5 diseases in open-access papers, as found by Europe PMC text mining. Sharing a sentence is not in itself a finding about the gene and the disease. The quoted sentences say what the papers report.
breast carcinoma (2 papers, 2022 to 2025). "The TAS2Rs with highest expression in HNSCC (TAS2R4, TAS2R14, TAS2R19, TAS2R20, TAS2R30, TAS2R43, and TAS2R45) overlap with TAS2Rs expressed at increased levels in breast cancer." (PMID 34717036, 2022).
Hypertension (1 paper, 2022). The presence of chronic increased pressure in the systemic arterial system. "A few functional mitochondrial alterations and TAS2R30 might be associated with a higher incidence of hypertension in Di-Qiang populations." (PMID 35864541, 2022).
TAS2R30 also shares sentences with these, for which no sentence is quoted: cancer (1 paper); glioma (1); melanoma (1).